IL1B (interleukin 1 beta)
Diseases named in the same sentence as IL1B in open-access papers (continued):
Sharing a sentence is not in itself a finding about the gene and the disease.
periodontal disease (267 papers, 2007 to 2026). "The ratio of M1 to M2 macrophages correlates positively with the severity of periodontal diseases, which is associated with the expression of pro-inflammatory cytokines IL-1β and MMP-9 in gingival tissues." (PMID 40871666, 2025). "IL-1β and MMP-8 serve as complementary salivary biomarkers for periodontal disease, with IL-1β associated with early inflammation and MMP-8 linked to advanced tissue destruction." (PMID 40283051, 2025). "Among these, the composite IL1 genotype, especially the combination of IL1A −889 C>T and IL1B +3954 C>T polymorphisms, has been most consistently linked to increased periodontal disease severity, particularly in European populations." (PMID 41300760, 2025). "The effects of IL-1β in the pathogenesis of periodontal disease are associated with increased tissue concentration." (PMID 39964474, 2025). "Another clinical study in adults confirmed significant associations between the severity of periodontal disease and salivary concentrations of IL-1β and TNF-α." (PMID 41301927, 2025). "Bone-related indicators such as BMD and BV/TV were positively associated with A. muciniphila abundance, while IL-1β levels were reduced, further supporting its protective role against periodontal disease progression." (PMID 41040884, 2025). "From the oral biocompatibility and anti-inflammatory perspectives, these cytokines (especially IL-1β) are the most clinically relevant cytokines when testing oral care products as they have been directly associated with gingivitis and periodontal diseases." (PMID 38786524, 2024). "IL-1β is strongly associated with dysbiosis, resulting in oral inflammation in patients with gingivitis and periodontal disease." (PMID 39338495, 2024). "Gingivitis is an inflammation of the gums that is the initial cause of the development of periodontal disease by the activity of Nuclear Factor-kappa B (NF-κB), Interleukin-1β (IL-1β), Interleukin-6 (IL-6), p38, and Tumor Necrosis Factor-α (TNF-α)." (PMID 38978754, 2024). "Many studies have reported that IL1B polymorphisms affect susceptibility to periodontal disease and its progression." (PMID 39258145, 2024). "Literature shows that elevated IL-1β levels in the saliva are associated with deeper probing depths in periodontal disease patients." (PMID 38192959, 2023). "The result is a strong or weak GCF exudation trait that determines periodontal disease susceptibility, depending on which SNP variants of IL1B at −511 and +3954 are present in the genome." (PMID 37762554, 2023). "Periodontal disease in dogs is associated with an increased production of IL-1B and IL-8 in the presence of increased COX-2." (PMID 37237883, 2023). "The authors identified that MMP-8, MMP-9, OPG, and IL-1β demonstrated a strong association with periodontal disease progression." (PMID 35626325, 2022). "Periodontal diseases increase levels of circulating IL-1β, IL-6, IL-8, IL-17 and TNF-α, interleukins associated with systemic inflammation and preterm birth." (PMID 35369278, 2022). "There is strong evidence that PRF has anti-inflammatory properties and pyroptosis is linked to the activation of the inflammasome and release of IL-1β in periodontal disorders." (PMID 35955441, 2022). "Comparative levels of salivary IL-1β can therefore be potentially used as a diagnostic tool for the identification of periodontal disease progression along with clinical parameters." (PMID 35270581, 2022). "Reduced susceptibility to periodontal disease was present in IL-1A−889 and IL-1B+3953 C/C homozygotic patients." (PMID 36429405, 2022). "As for C5, it was reported that C5a can induce the activation of C5Ar in a murine periodontal disease and cause significant bone loss with the help of cytokines like IL-17, IL-1β, IL-6, and TNF." (PMID 35571048, 2022). "Interleukin-1β (IL-1β) is known to be involved in the immunopathology of periodontal diseases and has been implicated in the destruction of bone." (PMID 33390812, 2021).
periodontal disease (continued). "IL-1β is an inflammatory cytokine associated with innate immune response, inflammation, pathogenesis, and progression of periodontal disease." (PMID 33717115, 2021). "The elevated production of tumor necrosis factor‐α, IL‐1β, and IL‐6 have also been observed in patients with periodontal disease, which further leads to PDL destruction and attachment loss." (PMID 33270996, 2021). "Numerous studies have reported that the IL-1β polymorphisms affect the susceptibility to periodontal diseases and their progression." (PMID 31900383, 2020). "Further, subjects with IL1β gene polymorphisms showed increased levels of “orange” and “red” complex periodontal pathogens, which are considered as the main cause of periodontal diseases." (PMID 33081038, 2020). "Although the expression of proinflammatory cytokines associated with periodontal disease pathogenesis (such as, IL-1β, IL-6, IL-17A, and TNF) was inhibited, statistical significance was reached only for IL-17A, which was downregulated by 4.9-fold." (PMID 31581596, 2019). "In RAW macrophages, PBMCs and transgenic mice, the IL37 variant increases expression of IL-1β and IL-6, inducing more severe periodontal disease, while IL-37 protein production is impaired and shows reduced cleavage by caspase-1." (PMID 30206230, 2018). "IL-1β was also examined since this inflammatory cytokine has been associated consistently with severity of periodontal disease and as a stimulator of bone resorption in adults." (PMID 28253297, 2017). "We also aimed to analyse the association between the severity of the periodontal disease in diabetic patients and the increase in interleukin levels (IL-6, IL-1β and PGE2)." (PMID 29075409, 2017). "Association between interleukin-1 beta (IL-1β) rs1143627 polymorphism and periodontal disease susceptibility was inconsistent; hence we performed this meta-analysis to explore the precise correlation between them." (PMID 28404906, 2017). "They showed a positive association between the local expression of IL-1β and severity of periodontal disease." (PMID 25299619, 2014). "Elevated levels of MMP-8 and IL-1β in saliva are linked to periodontal disease progression." (PMID 39958008, 2025). "Furthermore, in T2DM there is an increase in TNF-α, IL-1β, IL-6, and IL-18, which are known to elevate HbA1C, which increases the risk for periodontal disease." (PMID 37629193, 2023). "In addition, patients with periodontal disease are shown to have genetic predisposition for increased cytokine secretion, particularly IL-1β and TNF-α." (PMID 33672708, 2021). "Similarly, IL‐1β stimulated the engagement of inflammatory cells, and the production of enzymes has been implicated in the pathogenesis of periodontal diseases." (PMID 33270996, 2021). "The pro‐inflammatory cytokine IL‐1β has been implicated as a key cytokine in periodontal disease." (PMID 29744188, 2017). "The main problem related to periodontal disease is bone loss, which is caused by activation of lymphocyte pro-inflammatory cytokines, such as IL-1β and TNF-α, and may be mediated by significant increases in IL-10 levels." (PMID 24819928, 2014). "The carriage of certain alleles of IL-1α and IL-1β is associated with the incidence and the severity of periodontal disease, in particular chronic periodontitis (CP), because these carriers produce more IL-1 in response to plaque than genotype negative individuals." (PMID 23046796, 2012). "In addition, periodontitis causes the secretion of cytokines such as TNF-α, IL-1β, and IL-6, leading to systemic inflammation, which may connect periodontal disease to a number of systemic problems, such as cardiovascular and neurological conditions." (PMID 40243684, 2025). "Thus, the IL-1β release into the cell supernatant is a hallmark for pyroptosis-mediated membrane perforation as it might occur in periodontal disorders." (PMID 35955441, 2022).
periodontal disease (continued). "However, elevated levels of TNF-α, IL10, IL-6, IL-1β and IL-8 were observed in the CP group, which may increase the susceptibility and progression of periodontal disease in these individuals." (PMID 32509226, 2020). "The role of IL-1β in periodontal disease activity highlights the inflammatory stage, while MMP-8 represents tissue breakdown." (PMID 40283051, 2025). "The cytokine profile observed—characterized by significant increases in IL-1β, IL-6, TNF-α, and IL-8—indicates that candidiasis in children is associated with an inflammatory state similar to that observed in early-onset periodontal disease." (PMID 41301927, 2025). "A cytokine of the first innate response to occur in the pathogenesis pathway of periodontal disease is interleukin-1 beta (IL-1β) an important pro-inflammatory mediator characteristically associated with inflammatory cell migration and osteoclastogenesis." (PMID 39964474, 2025). "For example, a study demonstrated that biomarkers such as MMP-8 and interleukin-1β (IL-1β) are significantly elevated in saliva in patients with periodontal disease compared to healthy individuals." (PMID 39958008, 2025). "IL-1β constitutes a pivotal pro-inflammatory cytokine that mediates the host immune response in periodontal disease." (PMID 40802302, 2025). "This study aimed to evaluate levels of salivary and gingival crevicular fluid (GCF), interleukin − 1 beta (IL-1β), interleukin − 10 (IL-10), and Metrnl in periodontal disease." (PMID 39964474, 2025). "Salivary concentrations and GCF total amount of IL-1β were significantly higher in the periodontal disease groups (p < 0.001)." (PMID 39964474, 2025). "IL-1β levels in gingival tissues and gingival crevicular fluids correlate with the inflammatory status of periodontal disease, suggesting that IL-1β induced by dental calculus contributes to the inflammatory responses in periodontal tissues." (PMID 40559160, 2025). "In this study, we focused on exploring the key crosstalk genes shared by AAA and periodontal disease (IL1B, PTGS2, and SELL) through comprehensive bioinformatics methods and validated using an external independent dataset." (PMID 40857330, 2025). "A three-group meta-analysis showed that immunotherapy affected periodontal disease progression by modulating local immune factors IL-1β, IL-17, IL-6, IL-8 and TNF-α, thus providing a potential statistically significant benefit." (PMID 41356100, 2025). "Collectively, the data support a reduction in host mediators (e.g., TLR-ATP, IL-1β, MMP-1, and MMP-9) with regimen treatment that are implicated in inflammation and periodontal disease destruction." (PMID 41303313, 2025). "Our results were consistent with studies reporting increased salivary concentrations and GCF total amount of IL-1β in periodontal disease." (PMID 39964474, 2025). "In our study, the evaluation of IL-1β revealed its potential to distinguish between healthy and periodontal disease groups and reflect periodontal inflammatory status." (PMID 39964474, 2025). "The regimen reduced pathogenic bacteria, IL-1β, MMP1, and MMP-9, paralleling clinical reductions in periodontal disease." (PMID 41303313, 2025). "IL-6 and IL-1β are both proinflammatory cytokines with established involvement in periodontal disease pathogenesis and drug induced gingival enlargements." (PMID 40182222, 2025). "Several other salivary diagnostic markers—such as interleukin-1β (IL-1β), matrix metalloproteinase-8 (MMP-8), and bacterial DNA—have also been studied in relation to periodontal disease." (PMID 40725658, 2025). "Previous studies have shown that periodontal disease is caused by bacteria present in dental plaque, which induce the production of inflammatory cytokines, such as TNF-α, IL-1β, and IL-6, thereby forming a cytokine cascade." (PMID 41303285, 2025). "IL-1β is one of the earliest and most potent pro-inflammatory cytokines involved in periodontal disease." (PMID 41155385, 2025).
periodontal disease (continued). "Given the inflammatory nature of periodontal diseases, gingivitis is also linked to increased levels of salivary inflammatory cytokines, including IL-6, TNF-α, IL-1β, IL-8, and IL-10." (PMID 40243684, 2025). "The comparison of these results emphasizes the varying diagnostic usefulness of IL-1β and MMP-8 across different stages of periodontal disease." (PMID 40283051, 2025). "These cytokines include interleukin-1 beta, interleukin-6, and tumour necrosis factor alpha, which are established biomarkers for periodontal diseases." (PMID 40310396, 2025). "The mRNA levels of IL-6 and IL-1β are elevated in tissues affected by both periodontal disease and peri-implantitis." (PMID 39650553, 2024). "The cytokines most implicated in periodontal disease include TNF-α, IL-1β, IL-6, IL-17A, INF-γ, IL-8, and, to a lesser extent, IL-12 and IL-18." (PMID 39062000, 2024). "Interleukin-1β (IL-1β) is a key pro-inflammatory cytokine that plays a crucial role in the pathogenesis of periodontal disease." (PMID 39275315, 2024). "IL-1β was one of the first cytokines suggested as a relevant biomarker for periodontal disease and has shown promise in early periodontal diagnosis using saliva." (PMID 39125970, 2024). "The baseline salivary MMP-8 and IL-1β levels of the periodontal disease groups were greater than those of the healthy subjects." (PMID 38086426, 2024). "Cytokines, including IL-1A, IL-1B, IL-10, and IL-6, released during gastrointestinal disturbances, are pivotal in driving the inflammatory response in periodontal disease." (PMID 39200318, 2024). "IL-1β is an important pro-inflammatory cytokine in the pathogenesis of periodontal disease since it is responsible for activating endothelial cells and facilitating the adhesion of eosinophils, thereby increasing the inflammatory response." (PMID 39456446, 2024). "IL-1β is a pro-inflammatory cytokine that is induced following host–microbiota interactions and plays a role in the pathogenesis of periodontal disease, influencing the expansion and activation of both Th1 and Th2 cells." (PMID 39682721, 2024). "These advanced sensors significantly improve the detection and monitoring of ALP and IL-1β levels in saliva, aiding in the early diagnosis of periodontal diseases." (PMID 39554809, 2024). "Individuals with good oral health have high levels of salivary TNF-α, IL-17, and IL-10, while individuals with periodontal diseases have increased levels of IL-1β and IL-6." (PMID 39338495, 2024). "The involvement of IL-1 in periodontal disease was mentioned for the first time in 1985; then, in 1991, the role of the IL-1β subunit was demonstrated." (PMID 38391885, 2024). "Gomeset al.25 noted that salivary IL-1β and TNF-α levels increase in periodontal disease and are associated with the onset and increased severity of the disease, and that their levels decrease after treatment." (PMID 37224312, 2023). "During the periodontal disease progression, circulating levels of pro-inflammatory cytokines increase, including interleukins (IL-1β, IL-2, IL-6, IL-8)." (PMID 37936877, 2023). "In particular, IL1β and IL-6 have shown to be elevated in subjects with periodontal disease, although both pro-inflammatory and anti-inflammatory cytokines have also been implicated in periodontal disease." (PMID 36319939, 2023). "Increased IL-1β in the saliva of patients with periodontal disease was also observed in previous studies by our group." (PMID 39935548, 2023). "Lastly, several studies reported elevated interleukin 1-β (IL-1β) salivary levels, which further corroborate the role of periodontal disease in activating pro-inflammatory pathways." (PMID 36981618, 2023). "This scoping review highlights the immune-related similarities between the COVID-19 infection and periodontal disease, especially focusing on serum cytokine levels, such as IL-1β, IL-6, and TNF-α levels." (PMID 37106750, 2023).
periodontal disease (continued). "The positive correlation between IL1β protein concentrations in saliva and many periodontal disease parameters suggests its usefulness as a biomarker for understanding oral conditions, as reported in the previous study." (PMID 36678235, 2023). "Periodontal diseases can affect overall health by altering the levels of adipokines (IL-1β, leptin, resistin, and adiponectin) in the serum, saliva, and GCF of obese female patients." (PMID 36767065, 2023). "IL-1β is a key cytokine in periodontal diseases because of its dual function in collagen degradation and effects on enhancing bone resorption and inhibiting bone formation." (PMID 35986791, 2022). "Given that the production of proinflammatory cytokines lies at the heart of periodontal diseases, we next utilized qRT–PCR and ELISA to examine the mRNA levels of TNFα, IL-6, and IL-1β in gingival tissues and related protein levels in mouse serum." (PMID 35588785, 2022). "A number of candidate gene studies showed that IL1A, IL1B, IL4, IL6, IL10, TNFA, FcγR, VDR, TLR2, TLR4, and MMP1 were the main genes associated with periodontal disease." (PMID 36294882, 2022). "According to some systematic reviews, our studied salivary molecules, IL-1β, IL-6, and MMP-8 are recognized as key salivary biomarkers with acceptable diagnostic reliability for periodontal disease." (PMID 35368315, 2022). "IL-39 levels were elevated in the presence of periodontal disease paralleling the increase in IL‐1β and periostin levels." (PMID 35986791, 2022). "Concentrations of four pro-inflammatory cytokines (IL-1β, IL-6, IL-8 and TNF-α) linked with periodontal disease were measured in the collected saliva of nine subjects in the probiotic gum group at each timepoint." (PMID 33962608, 2021). "These both concluded that IL-1β is the most robust salivary biomarker with respect to periodontal disease." (PMID 34001101, 2021). "The significant upregulation of pleckstrin levels in the presence of IL-1β or LPS in gingival cells further supports a potential role of this protein in the inflammatory response driving periodontal disease progression." (PMID 35087525, 2021). "During periodontal disease progression, IL-1β plays a pivotal role in the induction and maintenance of the host immune response, with a negative effect on periodontal soft tissues." (PMID 34069836, 2021). "The current study also pointed to Galcectin-3, NLRP3, IL-1b as an additional biomarker in crevicular fluid, which controls the progress of periodontal disease." (PMID 34829603, 2021). "After adjusting for age, the significant biomarkers for gingival bleeding and periodontal disease were IL-1β and IL-1α, respectively." (PMID 34199256, 2021). "The levels of IL-1β, IL-8, and IL-4 were higher in the patients with periodontal disease than in the healthy subjects, although the differences were not statistically significant." (PMID 34199256, 2021). "Pro-inflammatory cytokines, Tnfa and Il1b, have been shown to initiate bone resorption in periodontal diseases." (PMID 34903915, 2021). "From the results adjusting for age, the significant biomarkers were IL-1β and IL-1α for gingival bleeding and periodontal disease, respectively." (PMID 34199256, 2021). "The presence of the chemokine IL-8 induces the secretion of lymphocytes, monocytes, epithelial cells, fibroblasts, tumor cells, bone resorption, and IL-1β, indicating an ongoing inflammatory process and the progression of periodontal disease." (PMID 33717115, 2021). "Regarding these findings, it has been demonstrated that IL-1β plays a fundamental role in the pathogenesis of periodontal disease." (PMID 34299815, 2021). "The usefulness of IL-1β as a biomarker of periodontal disease was confirmed through sensitivity and specificity analysis." (PMID 34199256, 2021). "IL-1β and TNF-α are potent pro-inflammatory mediators secreted in response to bacteria and are associated with the pathogenesis and progression of periodontal disease." (PMID 32106858, 2020).